AQP9 (aquaporin 9)
Diseases named in the same sentence as AQP9 in open-access papers (continued):
Sharing a sentence is not in itself a finding about the gene and the disease.
laryngeal carcinoma (1 paper, 2022). Carcinoma that arises from the laryngeal epithelium. "By unsupervised cluster analysis, we constructed two molecular subtypes of laryngeal cancer using ConsensusClusterPlus package based on AQP9 and ZAP70 expression profiles." (PMID 35477402, 2022). "To investigate biological functions of AQP9 and ZAP70 during laryngeal cancer progression, we separately silenced and overexpressed AQP9 and ZAP70 in TU212 and LCC cells." (PMID 35477402, 2022). "Wound healing assay was carried out to investigate the effects of AQP9 and ZAP70 on migration of laryngeal cancer cells." (PMID 35477402, 2022). "Prognosis-related IRGs were then explored by univariate cox regression analysis and correction of clinical factors, AQP9, CXCL11, IGHV4.31, PDGFA and ZAP70 were significantly correlated to laryngeal cancer prognosis." (PMID 35477402, 2022). "Expression of AQP9 and ZAP70 was validated in laryngeal cancer tissues and cells by RT-qPCR and immunohistochemistry." (PMID 35477402, 2022). "Transwell assays were applied for evaluating the roles of AQP9 and ZAP70 on migration and invasion of laryngeal cancer cells." (PMID 35477402, 2022). "Firstly, although our data demonstrated the roles of AQP9 and ZAP70 on proliferation, migration and invasion of laryngeal cancer cells, exact molecular mechanisms deserve in-depth observation." (PMID 35477402, 2022). "Our data showed that up-regulation of AQP9 and ZAP70 suppressed proliferation, migration and invasion of laryngeal cancer cells." (PMID 35477402, 2022). "By RT-qPCR, we detected AQP9 and ZAP70 expression in 30 pairs of laryngeal cancer and adjacent control tissues." (PMID 35477402, 2022). "By univariate cox regression analysis, correction of clinical factors and multivariate cox regression analysis, two IRGs AQP9 and ZAP70 were significantly correlated to survival outcomes of laryngeal cancer." (PMID 35477402, 2022). "AQP9 and ZAP70 up-regulation distinctly suppressed proliferation, migration, and invasion of laryngeal cancer cells." (PMID 35477402, 2022). "RT-qPCR results demonstrated that AQP9 and ZAP70 mRNA expression was distinctly decreased by their siRNAs and was overexpressed by their overexpression plasmids in laryngeal cancer cells." (PMID 35477402, 2022). "This indicated that subtypes based on AQP9 and ZAP70 may reflect immune microenvironment of laryngeal cancer." (PMID 35477402, 2022). "Combining previous research, AQP9 and ZAP70 mediated laryngeal cancer progression." (PMID 35477402, 2022). "Our findings revealed the roles of AQP9 and ZAP70 in progression of laryngeal cancer, and suggested that AQP9 and ZAP70 could potentially act as candidate immunotherapeutic targets for laryngeal cancer." (PMID 35477402, 2022). "Low expression of AQP9 and ZAP70 was confirmed in laryngeal cancer." (PMID 35477402, 2022). "Two molecular subtypes based on AQP9 and ZAP70 may reflect immune microenvironment of laryngeal cancer." (PMID 35477402, 2022). "Our findings demonstrated that AQP9 and ZAP70 might be candidate therapeutic targets and prognostic signatures for laryngeal cancer, which may assist guide clinical therapy in the future." (PMID 35477402, 2022). "Furthermore, high expression of AQP9 and ZAP70 was significantly correlated to favorable survival outcomes compared to their low expression in laryngeal cancer." (PMID 35477402, 2022). "Therefore, AQP9 and ZAP70 were identified as prognostic IRGs of laryngeal cancer." (PMID 35477402, 2022). "Hence, AQP9 and ZAP70 might become candidate therapeutic targets and robust prognostic signatures for laryngeal cancer." (PMID 35477402, 2022).
lipid metabolism disorders (1 paper, 2021). "In the first part of this study, proteomics was used to determine the presence of lipid metabolism disorders in early CLI induced by CCl4, and then, aquaporin 9 (AQP9), which was speculated to play an important role in lipid metabolism, was a potential intervention target of CLI." (PMID 34659635, 2021).
lung neoplasm (1 paper, 2021). A benign or malignant, primary or metastatic neoplasm involving the lungs. "AQP9 was observed more down-regulated in all tumors found differential expressed like lung neoplasms, thyroid carcinoma (THYM) and up-regulated in ovarian serous cystadenocarcinoma (OV) and pancreatic adenocarcinoma (PAAD)." (PMID 34475994, 2021).
nasal polyp (1 paper, 2022). "Expression levels of ALOX5AP, AQP9, CCL13, EMR3, F13A1, GAPT, and NCF2 were significantly higher in nasal polyp samples from ACRSwNP patients compared with the expression levels in samples from healthy subjects." (PMID 36059464, 2022).
non-alcoholic steatohepatitis (1 paper, 2018). "In another report, AQP9 expression was shown to be reduced in patients with non-alcoholic liver disease (NAFLD) and non-alcoholic steatohepatitis (NASH), translating its downregulation into a compensatory mechanism against TG accumulation in fatty liver." (PMID 29914059, 2018).
nonalcoholic fatty liver (1 paper, 2019). "The purpose of this study was to investigate the effect of Qutanhuoxue decoction on AQP7 and AQP9 expression in nonalcoholic fatty liver model rats." (PMID 31275413, 2019).
Ornithine transcarbamylase deficiency (1 paper, 2022). "Ornithine transcarbamylase deficiency (OTCD), a urea cycle disorder, is characterized by insufficient AQP9 expression." (PMID 35883453, 2022).
osteoporosis (1 paper, 2015). A condition of reduced bone mass, with decreased cortical thickness and a decrease in the number and size of the trabeculae of cancellous bone (but normal chemical composition), resulting in increased fracture incidence. "For example, they could find direct relevance in osteoporosis based on the observations that Si interferes with aluminium deposition at the bone mineralization front, that bone turnover cells express certain AQGPs and that bone metabolism is impaired in AQP1−/− and AQP9−/− mice." (PMID 26313002, 2015).
polyp (1 paper, 2022). A usually exophytic mass attached to the underlying tissue by a broad base or a thin stalk. "Therefore, blocking AQP9 is a potential effective pharmacological approach for the abrogation of chronic inflammation and polyp growth." (PMID 36059464, 2022).
sarcopenia (1 paper, 2024). Progressive decline in muscle mass due to aging which results in decreased functional capacity of muscles. "The highlight of our study is the identification of six potential diagnostic markers for sarcopenia: BTG2, FOXO3, AQP9, SCN1B, CYCS, and GPC3." (PMID 39777262, 2024). "Six biomarkers—BTG2, FOXO3, AQP9, GPC3, CYCS, and SCN1B—were identified alongside a diagnostic model that offers a novel approach for early diagnosis of sarcopenia." (PMID 39777262, 2024).
scrapie (1 paper, 2019). A fatal disease of the nervous system in sheep and goats, characterized by pruritus, debility, and locomotor incoordination. "In this study using different methodologies, we have demonstrated the overexpressions of AQP1, AQP4 and AQP9 in the brains of several models of scrapie-infected mice during incubation times and at the terminal stage." (PMID 31814527, 2019). "Western blots revealed markedly increased levels of AQP1, AQP4 and AQP9 in the brain tissues of all tested scrapie-infected mice collected at terminal stage." (PMID 31814527, 2019). "We noticed remarkable enhanced expressions of AQP1, AQP4 and AQP9 in the brains of scrapie-infected animals at the terminal stage." (PMID 31814527, 2019). "Similarly, overlapped AQP9/PrP signals were also detectable in the brain sections of scrapie-infected mice." (PMID 31814527, 2019).
Sjögren’s syndrome (1 paper, 2025). "However, there are indications that patients with Sjögren’s syndrome (SS) have autoantibodies against AQP9." (PMID 40725460, 2025).
syndrome of inappropriate antidiuretic hormone (1 paper, 2025). "In contrast, AQP2 appears to reflect systemic neuroendocrine responses to injury (e.g., syndrome of inappropriate antidiuretic hormone—SIADH), and AQP9 may contribute to cellular adaptation via lactate and glycerol transport." (PMID 40564125, 2025).
testicular disorder (1 paper, 2013). A non-neoplastic or neoplastic disorder affecting the testis. "AQP-9 appeared to be focal or lacking in adolescent varicocele testes, suggesting AQP-9 to be downregulated in such testicular disorder." (PMID 24348160, 2013).
varicocele (1 paper, 2013). A condition characterized by the dilated tortuous veins of the spermatic cord with a marked left-sided predominance. "Moreover AQP-9 expression has also been investigated in normal and varicocele human testis." (PMID 24348160, 2013).
ZIKV infection (1 paper, 2021). "After ZIKV infection, the levels of AQP1 and AQP9 were significantly decreased, and the levels of other AQPs were increased at the transcriptional levels, which might result from the disruption of EEC." (PMID 33667230, 2021).
tumor (52 papers, 2010 to 2026). "In univariate analysis, low expression of AQP9 was associated with tumor size/number, TNM stage and lymph node/distant metastasis within HCC patients." (PMID 31969493, 2020). "Nevertheless, the underlying function and mechanisms of AQP9 in tumor progression and tumor immunology remain unelucidated." (PMID 33247170, 2020). "Elevated AQP9 was significantly associated with B cell, T cell, monocyte, macrophage, tumor-associated macrophage, and neutrophil cell infiltration (p < 0.05), leading to a general increase in immune infiltration." (PMID 31703694, 2019). "Association analysis showed that the decline of AQP9 level was relevant with the stage of tumor, tumor differentiation and tumor metastasis (P < 0.01)." (PMID 27329843, 2016). "This correlation at the transcript level was confirmed by co-immunolocalization of calgranulin B and AQP9 in tumor-associated myelomonocytic cells, which include neutrophils." (PMID 24086629, 2013). "AQP9 has also been linked to tumor progression, particularly in HCC." (PMID 39796114, 2024). "To gain more detailed insights into the underlying functions of AQP9 in tumor immune as well as its regulatory mechanism, we conducted bioinformatics analysis to guide further research as well as provide a biomarker for prognosis and clinical treatment in multiple cancers." (PMID 33247170, 2020). "Furthermore, univariate analysis suggested that low-expression of AQP9 in HCC patients was associated with tumor size/number, TNM stage and lymph node/distant metastasis." (PMID 31969493, 2020). "AQP9 was also significantly correlated with the regulation of tumor associated macrophages (TAM)." (PMID 33247170, 2020). "And high AQP9 expression level was found to be positively associated with tumor grade and histological type, they therefore proposed that overexpression of AQP9 might represent an important factor in ovarian carcinogenesis." (PMID 29472315, 2018). "We also found a strong clinical association between AQP9 level and tumor differentiation grade." (PMID 28640255, 2017). "AQP9 low expression was significantly associated with poor tumor differentiation (P=0.004)." (PMID 28640255, 2017). "Moreover, we found that AQP9 functions as a drug transporter and further sensitized tumor cells to chemotherapy drugs associated with RAS signaling activation." (PMID 28640255, 2017). "These collective findings indicate that the relationship between glucose and chemosensitivity might be associated with not only tumor metabolism but also AQP9 level and consequent drug uptake efficiency in cancer cells." (PMID 28640255, 2017). "Consequently, we reason that a major effect of AQP9 expression on tumor associated edema is unlikely." (PMID 24086629, 2013). "At the same time, AQP9 was associated with the expression of macrophages and the inhibition of the recruitment of NK and CD8+T cells in the tumor microenvironment." (PMID 35245343, 2022). "We found that AQP1 (5.83e−07), AQP2 (0.0146), AQP4 (0.000382), AQP6 (0.0221), AQP7 (0.00052), AQP9 (8.2e−07) had significant correlations with the pathological stages of the tumor." (PMID 35245343, 2022). "We found that the expression of AQP9 was positively correlated with B cell, macrophage, neutrophil, and dendritic cell, which indicated that AQP9 had a certain relationship with the tumor inflammatory microenvironment." (PMID 35245343, 2022). "In CD8+ T cells, AQP9 was required for longevity and fast response to rechallenge, and to cell locomotion in reaching the tumor microenvironment." (PMID 35883453, 2022). "ATO’s capability to block tumor proliferation was positively related with Pin1 degradation and AQP9 presence and Pin1 degradation." (PMID 36077720, 2022). "So, ATO absorption through AQP9 controls the capability to provoke Pin1 degradation and block tumor proliferation." (PMID 36077720, 2022). "AQP9 downregulation was also correlated with tumor extension, survival rate, and lymphatic and distal metastasis." (PMID 35883453, 2022).
tumor (continued). "At the same time, the expression of AQP9 was significantly up-regulated with the increase of tumor grade, and the expression of AQP9 was up-regulated." (PMID 35245343, 2022). "Consistent with the results of TCGA, AQP9 was significantly higher in tumor tissues (p < 0.001), and higher AQP9 levels were associated with shorter overall survival duration (p = 0.044)." (PMID 34804972, 2021). "AQP9, a member of the aquaporin family, is involved in development of several tumors, promoting the proliferation, migration and invasion of tumor cells." (PMID 34012923, 2021). "AQP9 had significant association with various immune infiltrating cells including CD8+ and CD4+ T cells, neutrophils, tumor associated macrophages (TAMs) and dendritic cells (DCs)." (PMID 34012923, 2021). "AQP9 was associated with the expression levels of M2, tumor-associated macrophages (TAMs), and the recruitment of CD8+ T cells in tumor environment." (PMID 34804972, 2021). "In the subsequent analysis, a simple linear regression was performed on the AQP9 levels of different stages, and the results verified that the AQP9 expression level was positively correlated with the tumor stage (R2 = 0.5217, p < 0.001)." (PMID 34804972, 2021). "It was observed in the tumor center that when the tumor tissue presented a high AQP9 level, the infiltration of CD8+ T cells was significantly blocked." (PMID 34804972, 2021). "In the present study, our results indicated that the mRNA levels of AQP9 were remarkably down-regulated in HCC patients with larger tumor diameter (≥5cm), lymph node metastasis and advanced TNM stage (III-IV)." (PMID 31969493, 2020). "The expression of AQP9 was significantly down-regulated in HCC patients with larger tumor diameter (≥5cm), lymph node metastasis and advanced TNM stage (III-IV)." (PMID 31969493, 2020). "In summary, our study performed integrated analyses for the significance of AQP9 in prognosis and its potential role in tumor-immune interaction." (PMID 33247170, 2020). "In vivo studies indicated that tumor volume and weight were remarkably decreased in AQP9 overexpression group, where the levels of Wnt/β-catenin signaling- and EMT-associated molecules were also reduced." (PMID 31969493, 2020). "To evaluate the discrepancies of AQP9 mRNA expression levels in different tumor and normal tissues, we analyzed the Oncomine database to determine the AQP9 expression in multiple cancers." (PMID 33247170, 2020). "Eventually, it was found that AQP9 expression level was significantly correlated with both clinical prognosis and tumor-infiltrating immune cells in BRCA, COAD, LUAD, LUSC and STAD." (PMID 33247170, 2020). "In conclusion, AQP9 expression had a significant impact on the regulation of immune infiltration levels and tumor-immune interaction in BRCA, COAD, LUAD, LUSC and STAD." (PMID 33247170, 2020). "For example, our analyses are more based on the public databases, and the detailed molecular biological mechanisms in which AQP9 is involved to regulate the tumor infiltration need to be further validated." (PMID 33247170, 2020). "AQP9 is a water/glycerol channel protein with a broad substrate spectrum and is reported to serve as a significant part in the tumorigenesis and tumor progression." (PMID 33247170, 2020). "Although differential AQP9 expression was detected between tumor and normal tissues, the prognostic implication of this finding has not been demonstrated." (PMID 31703694, 2019). "To validate AQP9 mRNA expression in ccRCC tissues, we performed RT-qPCR in 380 paired tumor and normal samples with available clinical follow-up data from FUSCC cohort." (PMID 31703694, 2019). "This study investigated AQP9 expression in tumor tissues and defined the prognostic value in ccRCC patients." (PMID 31703694, 2019). "To validate AQP9 mRNA expression profile in ccRCC tissues, we performed RT-qPCR using 380 paired tumor and normal samples with available clinical follow-up data from a real-world cohort." (PMID 31493764, 2019).